HIF1A (hypoxia inducible factor 1 subunit alpha)
Diseases named in the same sentence as HIF1A in open-access papers (continued):
Sharing a sentence is not in itself a finding about the gene and the disease.
glioblastoma (continued). "Under both uninterrupted and cycling hypoxic stress, HIF-1α and NF-κB protein levels increased in U87 or U251 glioblastoma cell nuclei." (PMID 26711814, 2015). "Our results from the growth reduction analysis showed that glioblastoma growth was more sensitive to the removal of feedback from IGFBP2 to HIF1α as compared to the IGFI to HIF1α interaction." (PMID 25884993, 2015). "There have not been any published drugs that have specifically blocked feedback between IGFBP2 and HIF1α in glioblastoma." (PMID 25884993, 2015). "The expression levels of LOX, BMP1 and HIF1A were correlated and analyzed according to IDH1 mutation status and to the clinical end-point of overall survival of glioblastoma patients." (PMID 25790191, 2015). "Our previous studies indicated that NADPH oxidase subunit 4-mediated ROS contributes to the cycling hypoxia-induced HIF-1α activation in glioblastoma cells." (PMID 26711814, 2015). "Current literature data on the relationship between HIF1α and oxygen shows that glioblastoma growth is insensitive to high oxygen levels, but highly sensitive at low oxygen concentrations." (PMID 25884993, 2015). "Cycling hypoxia-induced Bcl-xL expression via ROS-mediated HIF-1α and NF-κB activation plays an important role in the tumor microenvironment-promoted anti-apoptosis and chemoresistance in glioblastoma." (PMID 26711814, 2015). "In our predictions, removing the feedback from IGFBP2 to HIF1α resulted in almost half of the growth in the glioblastoma diameter over 40 days as compared to removing the downstream signal from IGFI to HIF1α." (PMID 25884993, 2015). "Taken together, these results indicate that cycling hypoxia promotes HIF-1α and NF-κB activation in glioblastoma cells via ROS." (PMID 26711814, 2015). "For the remaining initial conditions, the insulin signaling system in glioblastoma was robust over changes in initial HIF1α concentrations and the (IGFI-IGFBP2) complex concentration." (PMID 25884993, 2015). "Our sensitivity analysis on the rate constants showed that the contribution of basal HIF1α production to LN229 glioblastoma growth is greater than contribution of the IGFI-dependent HIF1α production." (PMID 25884993, 2015). "In contrast, our results show that cycling hypoxia induces HIF-1α and NF-κB activation through ROS generation and this activation dramatically decreases after Tempol treatment in both U87 and U251 glioblastoma cells." (PMID 26711814, 2015). "Bcl-xL expression and anti-apoptotic effects were upregulated under cycling hypoxia in glioblastoma cells concomitantly with decreased responses to TMZ through ROS-mediated HIF-1α and NF-κB activation." (PMID 26711814, 2015). "This suggests that HIF1α would be a more effective target to reduce glioblastoma growth than targeting the IGFIR molecular interactions by current drugs." (PMID 25884993, 2015). "A previous report demonstrated that the reduction in LDH expression is mediated by a reduction in HIF1A following inhibition of the PI3K signaling pathway in adult glioblastoma." (PMID 25084455, 2014). "These, in turn, stabilize HIF-1α in a hypoxia-independent manner to promote glioblastoma progression." (PMID 25084196, 2014). "As previously shown in glioblastoma cells, hypoxia and HIF-1α can regulate the expression of CXCR4 in colon cancer cell lines." (PMID 24629239, 2014). "Phosphoprofilin (pY129) also facilitated glioblastoma progression by endothelial secretion of angiocrine factors that induced hypoxia inducible factor 1α (HIF1α) stabilization and accumulation in normoxic conditions." (PMID 25084196, 2014). "Many of the genes identified through this meta-analysis have in fact been implicated in development of astrocytoma including EGFR (amplification occurs in ∼40% of primary glioblastomas, HIF-1α, MYC, WNT5A, and IDH3A." (PMID 23737970, 2013).
glioblastoma (continued). "Research in glioblastoma multiforme has demonstrated HIF-1α to promote angiogenesis by inducing recruitment of mature F4/80+ macrophages in mice treated with bevacizumab." (PMID 23077404, 2012). "PTEN's loss of function results in HIF-1α activation by dysregulation of the PI3K/AKT pathway, especially in glioblastoma cells." (PMID 23391506, 2012). "The expression of HIF-1α is commonly increased in a variety of human solid tumors and elevated HIF-1α expression is associated with poor patient outcome in pancreatic, glioblastoma, gastric carcinomas, etc.." (PMID 22754381, 2012). "HIF-1α contributed to the induction of SDF-1α in glioblastoma cells, which in turn promoted tumor progression by recruiting MMP9+ vascular modulatory bone marrow cells." (PMID 20490273, 2010). "Downregulation of HIF-1α in response to zinc was demonstrable in vivo in a xenograft human glioblastoma model in nude mice using noninvasive bioluminescent imaging." (PMID 21179202, 2010). "Second, SDF1 expression is induced under hypoxic conditions in a glioblastoma tumor model system through HIF1α, suggesting that SDF1 expression is increased in rapidly growing tumors deprived of oxygen supply." (PMID 20087418, 2010). "Altogether, these data show that zinc inhibited VEGF expression and tube formation induced by glioblastoma CM and that HIF-1α was required for zinc-induced VEGF downregulation." (PMID 21179202, 2010). "A recent survey of malignant and normal tissues found that the expression of HIF-1α is commonly increased in a variety of human tumors including colorectal carcinoma and glioblastoma." (PMID 19128456, 2009). "In accordance, HIF-1α-mediated recruitment of bone marrow-derived myeloid cells modulating tumor angiogenesis has been shown in mouse models of glioblastoma." (PMID 19536297, 2009). "Our model could contribute to further elucidating the role of HIF-1α and evaluating the efficacy of the forthcoming therapies intended for glioblastoma." (PMID 40277699, 2025). "Overall, these findings suggest that targeting ROS could be an effective strategy for glioblastoma treatment by disrupting the HIF-1α-SERPINE1 signaling pathway that promotes tumor progression in hypoxic environments." (PMID 41009025, 2025). "Consequently, the LB-100-induced decrease in HIF-1α mRNA expression was followed by reduced MGMT gene transcription in MDR glioblastoma cells." (PMID 40006556, 2025). "Furthermore, melatonin destabilized hypoxia-induced HIF-1α protein via its antioxidant activity against ROS produced by glioblastoma cells in response to hypoxia." (PMID 40427575, 2025). "A significant limitation of radiation therapy is its reduced efficacy in hypoxic regions; however, HSP90 inhibition by NXD30001 and NVP-AUY922 has been shown to increase radiosensitivity in hypoxic CD133-positive subpopulations glioblastoma spheroids, likely due to HIF-1α inhibition." (PMID 39949745, 2025). "Specifically, LB-100 decreased HIF1α mRNA expression in MDR glioblastoma U87-TxR cells." (PMID 40006556, 2025). "These bioinformatics and computational analyses suggest that vortioxetine suppresses glioblastoma development by modulating the functions and activities of AKT1, HIF1A, CDH1, NFKB1, and associated signaling pathways, such as the Rap1, chemical carcinogenesis-ROS, and HIF-1 signaling pathways." (PMID 40312983, 2025). "HCMV US28 activates the HIF-1α/PKM2 axis in glioblastoma cells, resulting in increased VEGF and lactate secretion, as well as enhanced expression of HIF-1 target genes, including glucose transporter type 1 and glyceraldehyde-3-phosphate dehydrogenase, which are both involved in glucose metabolism." (PMID 41194660, 2025).
glioblastoma (continued). "Furthermore, hypoxia has been shown to promote carcinogenic effects in glioblastoma by directly and indirectly inducing H19 expression through hypoxia-inducible transcription factor 1 alpha (HIF-1α ) activity." (PMID 38987833, 2024). "Parkin has been shown to reduce HIF-1α levels in glioblastoma cells." (PMID 39408813, 2024). "Our findings align with the previous research indicating elevated HIF-1α expression across various cancer types, including renal cancer, glioblastoma, non-small-cell lung cancer, thyroid carcinoma, bladder cancer, cervical cancer, endometrial carcinoma, gastric cancer, and rectal cancer." (PMID 38610951, 2024). "The effects of oligomycin A on short-term hypoxia were investigated on the highly resistant human uveal melanoma Mum2B and U87 glioblastoma cells, results suggesting that the anticancer effects might be enhanced by preventing HIF-1α protein accumulation." (PMID 38667760, 2024). "Other drugs such as chlorpromazine, echinomycin, fenofibrate, and R50922/R59949 inhibit glioblastoma growth via several mechanisms, including the blockade of dopamine signaling, interference with the HIF1α-PDGFD/PDGFRα-AKT pathway, and the induction of apoptosis." (PMID 38893207, 2024). "Furthermore, IL-17 regulates glucose metabolism, angiogenesis, and adipogenesis in tumor tissue through increasing VEGF and HIF-1α expression, inducing glioblastoma growth in vivo." (PMID 38918274, 2024). "Besides, HIF-1α is a metabolic switch between glycolysis-driven migration and oxidative phosphorylation-driven immunosuppressive colonization in glioblastoma." (PMID 38778409, 2024). "Similarly, NRF2 knockdown in glioblastoma and ovarian cancer cells led to reduced HIF-1α levels, with a concurrent reduction in VEGF expression levels." (PMID 38424190, 2024). "In addition, the therapeutic landscape in glioblastoma is evolving with the emergence of new strategies targeting HIF1α-related axes." (PMID 38893207, 2024). "Several related factors influence HIF1α-mediated signaling pathways in glioblastoma." (PMID 38893207, 2024). "In addition, an association of HIF-1α with TLR9 expression has been established in which HIF-1α siRNA decreases TLR9 transcripts in glioblastoma multiforme (GBM) cells treated with insulin-like growth factor 1 (IGF-1) under normoxic conditions." (PMID 38069210, 2023). "HIF-1α expression was significantly reduced in the leading edge of the glioblastomas compared with the infiltrating zone and core (P < 0.001 core versus leading edge; P = 0.029 infiltrating zone versus leading edge), suggesting a lower level of hypoxia in the leading edge." (PMID 37324244, 2023). "Additionally, a decreased HIF-1α expression after KDELC2 suppression implied that KDELC2 expression induces glioblastoma tumorigenesis under nutrient-deprived conditions." (PMID 37107298, 2023). "Under hypoxia, HIF1a binds to the hypoxia- responsive element (HRE) on the promoter region of ALDOC, thus causing metabolic reprogramming or aberration of glycolysis to promote glioblastoma and ovarian cancer." (PMID 36945054, 2023). "Thus, the proliferative activity of glioblastoma cells and the content of HIF-1α were higher in tolerant to hypoxia rats, but the mortality associated with the tumor process and IL-1β level in them were lower than in susceptible animals." (PMID 37542119, 2023). "Similarly, induction of mitochondrial stress, activation of ISR and decrease of HIF-1α were detected in DOXY-responsive glioblastoma, astrocytoma, and medulloblastoma cells." (PMID 37973789, 2023). "Indeed, even if a positive correlation between [64Cu][Cu(ATSM)] and [18F]FMISO or HIF-1α has been shown in glioblastoma models, other studies highlighted the failure of [64Cu][Cu(ATSM)] to correlate with hypoxic markers contrary to [18F]FMISO." (PMID 38006431, 2023).
glioblastoma (continued). "Furthermore, the immunofluorescence results revealed that the shKDELC2-transfected GBM8401 cells had a lower HIF-1α expression than the shLuc-transfected glioblastoma cells." (PMID 37107298, 2023). "In glioblastoma subgroup, HIF-1α, VEGF, and LDH were significantly increased after RT." (PMID 36121548, 2022). "Similarly, PTEN expression inhibited HIF-1α stabilization in glioblastoma-derived cell lines with evidence suggesting AKT regulation involvement, although AKT is indirectly associated with HIF-1α phosphorylation." (PMID 36003773, 2022). "In addition, a number of studies report an increase in NHEJ under hypoxia as a result of HIF-1 activation in glioblastoma and squamous cell carcinoma, potentially due to HIF-1α-mediated upregulation of Ku70 and DNA-PK." (PMID 35626708, 2022). "In addition, it is known that hyperactivation of HIF-1α in the tumor leads to the ineffectiveness of radio- and chemotherapy and poor prognosis in glioblastoma." (PMID 36157351, 2022). "In addition to protein-coding genes, HIF-1α can activate the expression of numerous miRNAs under hypoxic conditions in glioblastoma." (PMID 36157351, 2022). "First, we elucidated whether treatment of the different glioblastoma cellular subtypes with 200 μM CoCl2 was able to stabilize hypoxia-inducible factor 1α (HIF-1α) levels in the cells, thus mimicking hypoxic conditions." (PMID 36012235, 2022). "Interestingly, the KDEL receptor (KDELR2) can also target and promote the growth of HIF1a through the mTOR signaling pathway to guide glioblastoma." (PMID 36474171, 2022). "In glioblastoma cell lines under hypoxia, HIF-1α can stimulate the expression of H19 by directly binding to the H19 promoter, or by up-regulating the expression of specific protein 1 (SP1) protein and then binding to the H19 promoter to promote the expression of H19." (PMID 36139386, 2022). "Furthermore, we found that TGF-β1 increases glycolysis and reduces mitochondrial respiratory capacity by promoting NOX4-dependent ROS-mediated HIF-1α nuclear accumulation and stabilization in glioblastoma cells." (PMID 34257808, 2021). "Furthermore, it was evidenced that, in a model of human glioblastoma, the hypoxia-induced accumulation of HIF-1α was correlated with an increase of IL-6 levels." (PMID 33679443, 2021). "As expected, TGF-β1 induced HIF-1α overexpression and nuclear accumulation, which might strengthen its activity in glioblastoma cells." (PMID 34257808, 2021). "Based on these findings, we hypothesized that TGF-β1 treatment increases HIF-1α expression by stimulating the PI3K/AKT pathway in glioblastoma cell lines." (PMID 34257808, 2021). "Although both HIF-1a and HIF-2a are expressed in macrophages, HIF-2a accumulation in tumor associated macrophages is correlated with high tumor vascularity and tumor grade in many cancers including glioblastoma." (PMID 32566921, 2020). "In addition, as previously shown, IL18 upregulated the expression of the transcription factor Hif1a, which promoted migration of glycolysis-driven Tregs in a glioblastoma mouse model." (PMID 32687059, 2020). "Specifically, in glioblastoma, HIF-1α promotes miR-215 biogenesis by enhancing the incorporation of pri-miR-215 into the microprocessor Drosha; then, increased miR-215 directly targets the epigenetic regulator lysine (K)-specific demethylase 1B (KDM1B) to enhance adaptation to the hypoxic niche." (PMID 32014012, 2020). "In addition, another study also showed Notch participated in hypoxia-induced EMT in colon cancer, ovarian cancer and glioblastoma with regulation of Snail and HIF-1α." (PMID 32322559, 2020). "However, methylation does negatively regulate HIF1α transcriptional activity, target gene expression, and glioblastoma multiforme cell migration." (PMID 33088284, 2020).
glioblastoma (continued). "Third, IL18 upregulated genes consistent with an effector phenotype that supports growth and proliferation, such as genes related to fatty acid biosynthesis (Dgat2, Scd2, Hacd3) and Hif1a, which promotes glycolysis as well as migration of Tregs in glioblastoma." (PMID 32687059, 2020). "Furthermore, HIF1α-K674me1/2 methylation by G9a/GLP impairs HIF1-dependent migration of glioblastoma cell lines." (PMID 33088284, 2020). "Nevertheless, the effect of borneol on glioblastoma growth and HIF-1a expression are still unclear." (PMID 32626528, 2020). "In vitro and in vivo experiments done using U87 glioblastoma multiforme cells and tumors showed that experimentally imposed cyclic hypoxia (0.5–1% O2, 1 h hypoxia; 30 min reoxygenation; 3 cycles) increased HIF-1α signaling and enhanced its stabilization in a ROS-dependent manner." (PMID 31382593, 2019). "Moreover, also in a glioblastoma model, we demonstrated that lncH19 controls both expression and activity of HIF-1a through miR-675." (PMID 30781795, 2019). "Previous studies showed that HIF-1α knockdown enhanced hypoxia-induced TF expression in human glioblastoma cells, endothelial cells, and podocytes, suggesting that HIF-1α may act to prevent excessive expression of TF in response to hypoxic conditions." (PMID 30634531, 2019). "Finally, the ubiquitin ligase activity of FBXO11 destabilizes and inhibits de novo synthesis of HIF-1a, thereby promoting the glioblastoma cell response to hypoxia and inhibiting angiogenesis." (PMID 31159774, 2019). "In hypoxic conditions, a mesenchymal shift mediated by HIF-1α is induced in glioblastoma cells." (PMID 30621209, 2019). "In addition, CXCR4 was reported to be upregulated under hypoxic conditions in glioblastoma, via HIF-1α and VEGF." (PMID 31336612, 2019). "U87MG cell line is glioblastoma with high expression level of HIF-1α under normoxia." (PMID 29498688, 2018). "However, other evidence indicates that hypothermia suppresses the expression of VEGF (and HIF-1α) by T98G cells (derived from human glioblastoma multiform) independently of changes in O2 consumption." (PMID 28326040, 2017). "Thus, molecular relationship between HIF-1α and IL-1β has been reported in glioblastoma cells, where IL-1β decreased HIF-1α levels and promoted apoptosis." (PMID 28106131, 2017). "We found that decreasing PTEN protein levels could maintain Hif-1α expression and elevate H19 RNA levels under hypoxia in Ln229 glioblastoma cells, and vice versa in U87 cells." (PMID 28327666, 2017). "Based on our results in this study, the ubiquitination of HIF-1α could be an important mechanism whereby Parkin downregulates HIF-1α in glioblastoma cells, which can be tested in future." (PMID 29180628, 2017). "Hif-1α also positively correlates with H19 in human glioblastoma samples depending on PTEN status." (PMID 28327666, 2017). "Indeed, RICTOR has been shown to impair c-Myc expression in glioblastoma cells and c-Myc is known to interact with HIF-1α in cancer cells." (PMID 28445935, 2017). "Given that a large number of EZH2 targets in the regulation of metabolism and tumorigenesis, we hypothesized that the actions of EZH2 in glioblastomas may be related to HIF1α." (PMID 27259264, 2016). "Furthermore, it has been shown that inhibition of FPR1-triggered ERK1/2 phosphorylation reduces nuclear translocation of HIF-1α in glioblastoma cells." (PMID 27323409, 2016). "However, at low oxygen levels, glioblastoma will have drastically higher HIF1α levels which result in a much different phenotype and growth rate." (PMID 25884993, 2015). "Similarly, a recent study showed that BMP2 can sensitize glioblastoma-stem-like cells to TMZ (500 μM) by downregulating both hypoxia-inducible factor-1α (HIF-1α) and MGMT." (PMID 26546412, 2015). "Therefore, ROS mediated HIF-1α and NF-κB activation is a crucial mechanism involved in cycling hypoxia-induced anti-apoptosis and chemoresistance in glioblastoma cells." (PMID 26711814, 2015).